GMFB (glia maturation factor beta)
Description:
This protein causes differentiation of brain cells, stimulation of neural regeneration, and inhibition of proliferation of tumor cells.
Synonyms: GMF
Tractability: PROTAC: ubiquitination databases record sites on it; its protein half-life has been measured.
Gene: Protein-coding gene on chromosome 14 (54,474,466 to 54,489,077, reverse strand). Ensembl gene ENSG00000197045.
Subcellular location (Human Protein Atlas): Cytosol; Nucleoplasm; Nuclear bodies
Gene Ontology:
Molecular function: Arp2/3 complex binding; enzyme activator activity; protein kinase inhibitor activity; actin binding
Biological process: actin filament debranching; negative regulation of Arp2/3 complex-mediated actin nucleation; nervous system development; protein phosphorylation
Cellular component: cortical actin cytoskeleton
Homologues: Orthologues: dog GMFB (100% identical), guinea pig GMFB (100% identical), pig GMFB (100% identical), chimpanzee GMFB (99% identical), macaque GMFB (99% identical), mouse Gmfb (98% identical), tropical clawed frog gmfb (93% identical), zebrafish gmfb (89% identical), rat Gmfb (80% identical), rabbit GMFB (78% identical), Drosophila melanogaster GMF (51% identical), Caenorhabditis elegans Y50D7A.10 (41% identical). Paralogues in human: GMFG (82% identical).
Diseases named in the same sentence as GMFB in open-access papers:
GMFB is named in the same sentence as 41 diseases in open-access papers, as found by Europe PMC text mining. Sharing a sentence is not in itself a finding about the gene and the disease. The quoted sentences say what the papers report.
glioblastoma (5 papers, 2015 to 2022). The most malignant astrocytic tumor (WHO grade IV). "Further, β-elemene inhibited the proliferation of U87 glioblastoma cells through the GMFβ-dependent inactivation of the ERK1/2-Bcl-2/Survivin pathway." (PMID 34641334, 2021). "GMFβ can inhibit the growth of C6 in rats and block the G0/G1 cell cycle of human HG-1 glioblastoma cells in vitro." (PMID 34641334, 2021). "The β-elemene-mediated potentiation of the efficacy of temozolomide on glioblastoma cells results from activation of the glia maturation factor β (GMFβ)/MAPK 3/6/p38 pathway." (PMID 26370907, 2015). "In conclusion, these results suggest that the antiproliferative effect of β-elemene on glioblastoma is through the ERK1/2-Bcl-2/Survivin pathway, which is dependent on the inactivation of GMFβ." (PMID 34641334, 2021). "Moreover, elevated PKCι level increases resistance to cisplatin in glioblastoma cells by suppressing GMFβ/p38 MAPK signaling and induces glioblastoma motility by coordinating the formation of a single leading-edge lamellipod." (PMID 36358843, 2022). "Therefore, β-elemene inhibits proliferation through crosstalk between GMFβ and ERK1/2, weakens the resistance of glioblastoma cells to temozolomide, and functions as a good chemosensitizer against TMZ in glioblastoma brain tumors." (PMID 34641334, 2021). "In addition, it has been reported that the antitumor effect of β-elemene was also mediated by GMFβ-dependent inactivation of the ERK1/2-Bcl-2/survivin pathway, which suggests that β-elemene is a promising chemosensitizer for temozolomide against glioblastoma tumors." (PMID 26370907, 2015).
Alzheimer disease (4 papers, 2015 to 2025). A progressive, neurodegenerative disease characterized by loss of function and death of nerve cells in several areas of the brain leading to loss of cognitive function such as memory and language. "In recent years, GMFB has been found to be aberrantly upregulated in Alzheimer’s disease and Parkinson’s disease." (PMID 34793551, 2021). "The expression of GMFB has been shown to be upregulated during some pathological conditions, including ovarian cancer, Alzheimer’s disease and Parkinson’s disease." (PMID 34793551, 2021).
serous ovarian carcinoma (4 papers, 2016 to 2022). "Two studies have shown that GMFB is a prognostic biomarker for astrocytomas and serous ovarian cancers." (PMID 35860559, 2022). "Besides, high GMFB expression was related to poor disease-free survival and overall survival in patients with SOC (serous ovarian cancer)." (PMID 27655328, 2016).
glioma (3 papers, 2016 to 2022). A benign or malignant brain and spinal cord tumor that arises from glial cells (astrocytes, oligodendrocytes, ependymal cells). "Increased GMFB expression was found highly associated with multiple types of cancer, including glioma and ovarian cancer, and GMFB overexpression was reported to be co-expression with poor prognosis in ovarian cancer and glioma." (PMID 34796110, 2021).
brain ischemia (2 papers, 2018 to 2022). Diminished or absent blood supply to the brain caused by obstruction (thrombosis or embolism) of an artery resulting in neurologic damage. "Consistent with our in vivo results, GMFB was also up-regulated in primary astrocytes subjected to OGD as a model of brain ischemia." (PMID 30191459, 2018). "In addition, previous studies have shown that glial maturation factor β (GMFB) in astrocytes is upregulated after cerebral ischemia, and this brain-derived GMFB can destroy pulmonary microvascular endothelial cells (PMVECs) by increasing ROS." (PMID 35432726, 2022).
breast carcinoma (2 papers, 2014 to 2021). "We initially used the Oncomine database to analyze the expression profiles, and found that the GMFB transcription levels were markedly higher in breast cancer, head and neck cancer and liver cancer compared to the normal tissues." (PMID 34796110, 2021).
ischemia (2 papers, 2014 to 2018). A hypoperfusion of the BLOOD through an organ or tissue caused by a PATHOLOGIC CONSTRICTION or obstruction of its BLOOD VESSELS, or an absence of BLOOD CIRCULATION. "The GMFB protein levels were increased in the penumbra in rats subjected to ischemia compared to those in the sham group, as indicated by a significant increase in the optical density." (PMID 30191459, 2018). "Since there is no such research work of GMFβ in stroke to date, in this study, we also investigated the expression change of GMFβ protein both in ischemia and in the treatment of EA with single-time or multiple stimulations." (PMID 25126102, 2014). "EA stimulation made notably suppression of GMFβ expression in the ischemic striatum (P < 0.05, versus ischemia group) at Rep 1 d with single-time EA but not at Rep 7 d with multiple EA." (PMID 25126102, 2014). "Our results showed that, in the ischemia group, GMFβ protein levels were significantly upregulated in the ischemic cortex (P < 0.05, versus sham group) and slightly increased in the ischemic striatum (P > 0.05, versus sham group) at Rep 1 d, whereas they were almost kept unchanged at Rep 7 d." (PMID 25126102, 2014). "We investigated whether GMFB was up-regulated in the lung or in the brain following ischemia." (PMID 30191459, 2018). "Since up to now, there is no research report on GMFβ function in ischemia; here, we further detected the protein levels of GMFβ in ischemic striatum and ischemic cortex after ischemia/reperfusion with or without EA stimulation." (PMID 25126102, 2014). "Since ischemia injury did not change GMFβ levels in both cortex and striatum in chronic phase, it might be suggested that GMF is not closely related to inflammation in secondary injury after stroke." (PMID 25126102, 2014).
liver cancer (2 papers, 2021 to 2022). An epithelial or non-epithelial malignant neoplasm that arises from the liver. "There is insufficient research on GMFB in tumors, and the pathogenic mechanisms of this gene in liver cancer remain unclear." (PMID 36401409, 2022).
osteoporosis (2 papers, 2023 to 2024). A condition of reduced bone mass, with decreased cortical thickness and a decrease in the number and size of the trabeculae of cancellous bone (but normal chemical composition), resulting in increased fracture incidence. "This molecular evidence can be used to interpret the results of this study and thus could be the molecular mechanism underlying the role of GMFB in the adipogenesis of BMSCs and the occurrence of osteoporosis." (PMID 39543090, 2024). "Since the deletion of GMFB in rats prevents oestrogen deficiency-induced osteoporosis, we next investigated whether the knockdown of GMFB expression would rescue the bone phenotype of OVX rats." (PMID 39543090, 2024). "Together, these findings suggest a pathological association of the GMFB with PMOP and highlight the potential of the GMFB as a therapeutic target for osteoporosis patients." (PMID 39543090, 2024). "To study the potential role of GMFB in bone formation and osteoporosis, we first examined the GMFB protein level in OVX rat bone tissues." (PMID 39543090, 2024). "Sp in the DS-30-treated diabetic rats, which indicated that DS-30, a small-molecule inhibitor of GMFB, had a therapeutic effect on osteoporosis." (PMID 37121966, 2023). "Furthermore, we found that GMFB shRNA treatment in vivo had protective effects on osteoporosis induced by OVX." (PMID 39543090, 2024). "Therefore, in the present study, we used an unconditional GMFB knockout rat model to investigate the function of GMFB in osteoporosis." (PMID 39543090, 2024). "Furthermore, we found that GMFB shRNA treatment in vivo had favourable effects on osteoporosis induced by OVX." (PMID 39543090, 2024). "However, whether GMFB participates in osteoporosis is unknown." (PMID 39543090, 2024). "However, the role of GMFB in the adipogenesis of BMSCs and the occurrence of osteoporosis has not been reported in detail." (PMID 39543090, 2024).
Cognitive impairment (1 paper, 2024). Abnormal cognition is characterized by deficits in thinking, reasoning, or remembering. "First, we evaluated the effect of GMFB inhibitor (GMFBi) and dual treatment on behavior and cognitive impairment." (PMID 37307824, 2024).
dental caries (1 paper, 2012). The decay of a tooth, in which it becomes softened, discolored, and/or porous. "The association signal is centered over a region of low recombination harboring 4 genes, CDKN3, CNIH, GMFB and CGRRF1 (none of which have known or biologically plausible roles in dental caries)." (PMID 23259602, 2012).
diabetes (1 paper, 2022). "An in vitro study showed that glia maturation factor beta (GMFB), upregulated in the vitreous at a very early stage of diabetes, can induce ferroptosis in RPE cells by impairing lysosomal acidification and ultimately damaging retinal function." (PMID 36506045, 2022).
Hyperglycemia (1 paper, 2024). An increased concentration of glucose in the blood. "Research by Liu and colleagues has shown that in diabetic rat models, hyperglycemia induces the secretion of GMFB by Müller cells, and elevated levels of GMFB can impair retinal function by altering the quantity and connectivity of RPE cells." (PMID 38994366, 2024).
neurodegenerative disease (9 papers, 2015 to 2025). A disorder of the central nervous system characterized by gradual and progressive loss of neural tissue and neurologic function. "Glia (GMFB) is a highly conserved growth and differentiation factor for glia cells and neurons, and it is closely associated with neurodegenerative diseases." (PMID 35860559, 2022). "Furthermore, GMFB expression is altered in several neurodegenerative diseases, suggesting that GMFB may be a suitable disease biomarker." (PMID 37307824, 2024).
tumor (7 papers, 2016 to 2022). "Univariate analysis by Cox proportional hazard model showed that GMFB, pathologic stage and tumor status were responsible for OS in HCC." (PMID 34796110, 2021). "In fact, NT cells treated with IL-10 produced tumor activator factors such as RhoA, the glia maturation factor beta, galectin-1, the isocitrate dehydrogenase subunit alpha, and the D-3-phosphoglycerate dehydrogenase." (PMID 31766635, 2019). "Furthermore, the multivariate Cox regression analysis confirmed that GMFB (P=0.039), pathologic stage(P<0.001) and tumor status(P=0.003) were independent factors for predicting the prognosis of HCC patients." (PMID 34796110, 2021). "In our study, the expression level of GMFB was significantly up-regulated in patients with HCC and positively co-expression with tumor node metastases (TNM) stage and histopathological grade of HCC." (PMID 34796110, 2021). "UNG, FUCA2, DERA, GMFB, TF, and SNX24 as significantly downregulated upon mir-145 over-expression, are expected to have elevated expressions in tumor samples considering low levels of miR-145 in several cancer types." (PMID 27655328, 2016). "In summary, this study identified GMFB as a novel independent biomarker and therapeutic target for KIRC, and it provides a helpful and distinct individualized treatment strategy for KIRC with a combination of molecular targets and tumor microenvironment." (PMID 35860559, 2022).
cancer (6 papers, 2016 to 2024). A tumor composed of atypical neoplastic, often pleomorphic cells that invade other tissues. "We found that GMFB was highly expressed in several types of cancer including HCC, and confirmed the expression level of GMFB was closely associated with the TNM stage, clinical stage, and poor survival rates in HCC." (PMID 34796110, 2021). "Deletion of GMFB in cancer cells significantly inhibited proliferation, migration, and invasion of cancer cells, downregulated the expression levels of some matrix metalloproteinases (MMPs), and increased mtDNA copy number and loss of mitochondrial transmembrane potential." (PMID 39179991, 2024). "Based on the correlation of Gmfb with OS and DFS in pan-cancer analysis, GMFB may be a promising novel prognostic factor for KIRC." (PMID 35860559, 2022). "We identified six genes including UNG, FUCA2, DERA, GMFB, TF, and SNX24 as significantly downregulated and two genes including MYL9 and TAGLN as significantly upregulated upon mir-145 over-expression in distinct cancer types." (PMID 27655328, 2016).
neurological disorders (1 paper, 2024). "GMFB is primarily isolated from astrocytes, and numerous studies have focused on the role of GMFB in neurological disorders." (PMID 39543090, 2024).
GMFB also shares sentences with these, for which no sentence is quoted: Parkinson disease (4 papers); astrocytoma (2); experimental autoimmune encephalomyelitis (2); schizophrenia (2); alopecia (1); bladder cancer (1); Cerebral ischemia (1); cervical cancer (1); cervical intraepithelial neoplasia (1); cognitive decline (1); colon tumor (1); head and neck cancer (1); head and neck squamous cell carcinoma (1); ischemic stroke (1); laminopathy (1); malignant glioma (1); memory impairment (1); multiple sclerosis (1); neuro-degenerative diseases (1); ovarian carcinoma (1); renal carcinoma (1); renal clear cell carcinoma (1); skin atrophy (1); Stroke (1).